STEAP3 (STEAP3 metalloreductase)
Description:
Integral membrane protein that functions as a NADPH-dependent ferric-chelate reductase, using NADPH from one side of the membrane to reduce a Fe(3+) chelate that is bound on the other side of the membrane. Mediates sequential transmembrane electron transfer from NADPH to FAD and onto heme, and finally to the Fe(3+) chelate (By similarity). Can also reduce Cu(2+) to Cu(1+) (By similarity). Mediates efficient transferrin-dependent iron uptake in erythroid cells (By similarity). Indirectly involved in exosome secretion by facilitating the secretion of proteins such as TCTP.
Synonyms: TSAP6; dudlin-2; STMP3; AHMIO2; dudulin-2; pHyde
Tractability: Small molecule: a structure with a bound ligand is known; it has a high-quality binding pocket. Antibody: UniProt places it where antibodies can reach, with medium confidence; UniProt predicts a signal peptide or a membrane-spanning region; its Gene Ontology location is reachable by antibodies, with medium confidence. PROTAC: ubiquitination databases record sites on it; its protein half-life has been measured.
Gene: Protein-coding gene on chromosome 2 (119,222,447 to 119,265,652, forward strand). Ensembl gene ENSG00000115107.
Subcellular location: Endosome membrane
Subcellular location (Human Protein Atlas): Cytosol; Nucleoli
Pathways (Reactome):
Signal Transduction: CDC42 GTPase cycle; RHOD GTPase cycle; RHOF GTPase cycle; RHOJ GTPase cycle; RHOQ GTPase cycle
Transport of small molecules: Transferrin endocytosis and recycling
Gene Ontology:
Molecular function: FAD binding; ferric-chelate reductase (NADPH) activity; heme binding; protein binding; cupric reductase (NADH) activity
Biological process: protein secretion; copper ion import
Cellular component: cytoplasm; multivesicular body; endosome; endosome membrane; plasma membrane
Genetic constraint (gnomAD): Loss-of-function variants: 38 observed, 39.23 expected, observed/expected ratio (o/e) 0.97, 90% interval 0.75 to 1.27. The upper end of that interval is the gene's LOEUF score, 1.27, which puts it in group 5 of 6, group 1 being the genes least tolerant of losing a copy. Missense variants: 652 observed, 668.62 expected, observed/expected ratio (o/e) 0.98, 90% interval 0.91 to 1.04. Synonymous variants: 281 observed, 301.17 expected, observed/expected ratio (o/e) 0.93, 90% interval 0.85 to 1.03.
Gene-disease validity (ClinGen):
ClinGen rates the evidence that STEAP3 causes each of these diseases.
severe congenital hypochromic anemia with ringed sideroblasts (autosomal dominant): Disputed.
Homologues: Orthologues: chimpanzee STEAP3 (99% identical), macaque STEAP3 (98% identical), rabbit STEAP3 (88% identical), guinea pig STEAP3 (88% identical), pig STEAP3 (88% identical), dog STEAP3 (87% identical), rat Steap3 (86% identical), mouse Steap3 (85% identical), tropical clawed frog steap3 (61% identical), zebrafish steap3 (51% identical). Paralogues in human: STEAP2 (50% identical), STEAP4 (42% identical), STEAP1 (29% identical), STEAP1B (22% identical).
Diseases named in the same sentence as STEAP3 in open-access papers:
STEAP3 is named in the same sentence as 72 diseases in open-access papers, as found by Europe PMC text mining. Sharing a sentence is not in itself a finding about the gene and the disease. The quoted sentences say what the papers report.
glioma (25 papers, 2016 to 2024). A benign or malignant brain and spinal cord tumor that arises from glial cells (astrocytes, oligodendrocytes, ependymal cells). "Among these six genes, ANG, IL1A, LOXL1, LOXL2, and STEAP3 played risk roles in the survival of glioma patients (HR > 1), while F5 was a potential protective factor (HR < 1)." (PMID 37891828, 2023). "In our study, we explored the prognostic value of ferroptosis-associated gene STEAP3 in glioma, and found that high levels of STEAP3 served as an independent poor prognostic prediction factor in glioma patients." (PMID 37009153, 2023). "Compared with normal brain tissue, STEAP3 was highly expressed in glioma and was significantly associated with poor prognosis." (PMID 37009153, 2023). "Another study found that higher levels of STEAP3 expression in gliomas were associated with worse prognosis for patients and promoted the proliferation and self-renewal of glioma stem cells." (PMID 37736551, 2023). "STEAP3, which encodes metalloreductase, is considered highly expressed in glioblastoma, and knocking down STEAP3 suppresses glioma cell proliferation and metastasis." (PMID 34568059, 2021). "In the opposite manner, loss of STEAP3 in glioma cells weaken the aggressive phenotypes accompanied by the inhibition of cell proliferation, invasion as well as sphere formation." (PMID 34790664, 2021). "STEAP3-associated prognostic signatures for glioma have also been reported." (PMID 37009153, 2023). "In malignant gliomas, STEAP3 is overexpressed, and STEAP3 knockdown suppresses glioma cell metastasis, proliferation, and clonality, in vitro and tumor growth in vivo." (PMID 38515856, 2024). "After treatment with different doses of DFO and erastin, the transcriptional activities of HMOX1, LTF, and STEAP3 were reduced in both U87 and U251 glioma cells, indicating that these genes played a role in iron metabolism regulation." (PMID 37545464, 2024). "STEAP3 was able to promote glioma migration and invasion and predicted poor prognosis, suggesting that STEAP3 is a potential target for glioma diagnosis and treatment." (PMID 38440354, 2024). "HMOX1, LTF, and STEAP3 knockdown in glioma cells significantly reduced cell proliferation, colony formation, migration, and malignant invasion." (PMID 37545464, 2024). "The data indicated that HMOX1, LTF, and STEAP3 had relatively higher expressions in glioma cells compared to most other cancer cell lines." (PMID 37545464, 2024). "According to the analysis of TCGA datasets and IHC staining from HPA database, glioma exhibited significantly high STEAP3 mRNA and protein expression." (PMID 37009153, 2023). "In primary gliomas, patients with lower STEAP3 methylation level had worse prognosis than those with higher STEAP3 methylation level." (PMID 37009153, 2023). "In conclusion, we identify seven ferroptosis-associated genes (SLC39A14, WWTR1, STEAP3, NOTCH2, IREB2, HIF1A, and FANCD2) in gliomas, all of which are highly expressed." (PMID 37978473, 2023). "Considering the consistent prognostic significance of STEAP3 in GBM and LGG, we further evaluated the prognostic value of STEAP3 in glioma." (PMID 37009153, 2023). "Subsequently, ROC curve analysis suggested that the AUC values of WWTR1, STEAP3, SLC39A14, NOTCH2, IREB2, HIF1A, and FANCD2 were all 1.000, indicating their potential as diagnostic biomarkers for gliomas." (PMID 37978473, 2023). "In this study, we aimed to investigate the clinical significance and biological function of STEAP3 in the tumorigenesis and progression of glioma." (PMID 37009153, 2023). "Secondly, it is necessary to conduct functional experiments to elaborate the biological mechanism of STEAP3 and tumor-immune interactions in glioma." (PMID 37009153, 2023). "Patients with higher STEAP3 expression had worse prognosis than those with lower STEAP3 expression in primary and recurrent gliomas, respectively." (PMID 37009153, 2023).
glioma (continued). "Firstly, gene expression analysis based on retrospective databases needs further investigations in large-scale prospective clinical cohorts to confirm the prognostic value of STEAP3 in glioma." (PMID 37009153, 2023). "Cg05270572, cg23164999, cg25845374, cg18643762, cg04749104, and cg25101327, were significantly negatively correlated with STEAP3 expression in glioma." (PMID 37009153, 2023). "STEAP3 emerged as an important protein that induces mesenchymal transition and stem-like traits in glioma." (PMID 35359663, 2022). "As a metalloreductase, STEAP3 regulates cellular iron uptake and homeostasis and promotes the malignant progression of gliomas." (PMID 33330074, 2020). "STEAP3 is overexpressed in malignant gliomas, and STEAP3 knockdown suppresses glioma cell proliferation, clonality and metastasis in vitro and tumor growth in vivo." (PMID 30591630, 2018). "Additionally, upregulated STEAP3 in gliomas facilitates tumour cell migration and invasion and is significantly associated with immune‐infiltrating cells, including macrophages and neutrophils, particularly M2 macrophages." (PMID 38809929, 2024). "HMOX1, LTF, and STEAP3 were identified as the most essential IMRGs in gliomas." (PMID 37545464, 2024). "These in vitro findings demonstrated that HMOX1, LTF, and STEAP3 could facilitate the malignant progression of glioma cells." (PMID 37545464, 2024). "STEAP3 expression was markedly elevated in high-grade and recurrent glioma patients." (PMID 37009153, 2023). "STEAP3 was up-regulated in glioma, and increased with tumor grade." (PMID 37009153, 2023). "Further study suggested that STEAP3 may contribute to the induction of glioma immunosuppressive microenvironment by regulating macrophage M2 polarization." (PMID 37009153, 2023). "Tumor immune infiltrate analysis showed that STEAP3 might influence the clinical outcome of glioma patients by regulating the tumor immune microenvironment, especially the formation of the M2 macrophages." (PMID 37009153, 2023). "In the present study, the findings showed that M2 macrophage markers CD163 and CSF1R were positively correlated with STEAP3 expression in glioma, suggesting that the function of STEAP3 might be related to the regulation of macrophage M2 polarization." (PMID 37009153, 2023). "Furthermore, we employed the RNAseq_693 dataset from CGGA database to cross-validate the role of STEAP3 in glioma." (PMID 37009153, 2023). "Survival analysis indicated that STEAP3 had prognostic significance only in glioma." (PMID 37009153, 2023). "In order to explore the role of STEAP3 in glioma, we first comprehensively analyzed STEAP3 expression profiles, methylation, and its clinical implications with datasets acquired from The Cancer Genome Atlas (TCGA) and the Chinese Glioma Genome Atlas (CGGA)." (PMID 37009153, 2023). "The results of wound healing assays revealed that knocking down of STEAP3 could significantly suppress glioma cells migration." (PMID 37009153, 2023). "The possible mechanism by which STEAP3 promotes glioma progression may be through the activation of TfR and the downstream ferritin-STAT3 pathway." (PMID 37009153, 2023). "Furthermore, multivariate Cox regression analysis indicated that STEAP3 was an independent prognostic factor in glioma." (PMID 37009153, 2023). "Multivariate Cox regression analysis indicated that WHO grade (HR = 1.974; 95% CI [1.435–2.716]; P < 0.001), IDH status (HR = 0.290; 95% CI [0.200–0.421]; P < 0.001), and STEAP3 expression level (HR = 1.450; 95% CI [1.045–2.013]; P = 0.026) were independent prognostic factors for glioma patients." (PMID 37009153, 2023). "Namely, these observations indicate that STEAP3 facilitated migration and invasion in glioma cells." (PMID 37009153, 2023). "In summary, STEAP3 has great potential as a prognostic biomarker and therapeutic target in glioma." (PMID 37009153, 2023).
glioma (continued). "In general, our study indicated that STEAP3 might function as a potential prognostic biomarker in gliomas through immune regulation." (PMID 37009153, 2023). "However, existing studies on the biological function and molecular mechanisms of STEAP3 in glioma are few in number." (PMID 37009153, 2023). "The mechanisms of STEAP3 upregulation in glioma are currently poorly understood." (PMID 37009153, 2023). "Together these results imply that the role of STEAP3 might be involved in the induction of immunosuppressive environment and may be a promising therapeutic target for glioma immunotherapy." (PMID 37009153, 2023). "A recent investigation suggested that STEAP3 might exert its function as an oncogenic mediator in glioma progression." (PMID 34819946, 2021). "However, researchers still need to explore the potential clinical practice and role of STEAP3 in the progression of human gliomas." (PMID 35111661, 2021). "It was also found that the expression of STEAP3 is up-regulated in glioma, bladder cancer, and colon cancer, whereas the expression of STEAP3 in hepatocellular carcinoma (HCC), breast cancer, and lung cancer is lower than that in normal tissues." (PMID 34778263, 2021). "Therefore, we explored the role of STEAP3 in glioma immune microenvironment." (PMID 37009153, 2023). "STEAP3 promoter hypomethylation may be the mechanism of upregulation in glioma." (PMID 37009153, 2023). "Therefore, we mainly studied the effect of STEAP3 in glioma." (PMID 37009153, 2023). "The CancerSEA database showed that STEAP3 may contribute to glioma progression by promoting EMT." (PMID 37009153, 2023). "In addition, STEAP3 not only regulates ferroptosis by enhancing TfR expression and inducing mesenchymal transition, but also has a direct influence on glioma cell proliferation, invasion, and sphere formation in vitro and on glioma growth in vivo." (PMID 36358495, 2022). "The expression of STEAP3 in glioma cells is higher than that in normal brain tissues, which could be regarded as a potential prognostic marker and reduce the overall survival of patients with glioma." (PMID 36358495, 2022). "Single‐cell analysis of data from purified malignant glioma cells showed that HMOX1, LTF, and STEAP3 were predominantly expressed in mesenchymal‐like cell clusters facilitating intratumoral mesenchymal shift over time." (PMID 37545464, 2024). "Seven ferroptosis-related hub genes, namely SLC39A14, WWTR1, STEAP3, NOTCH2, IREB2, HIF1A, and FANCD2, were identified, all of which were highly expressed in glioma." (PMID 37978473, 2023). "Elevated expression of STEAP3, an iron reductase in the STEAP family, enhances glioma cell migration and invasion." (PMID 37978473, 2023). "In contrast to STEAP3, the roles of ARL9 and CMYA5 in glioma have rarely been reported and remain obscure." (PMID 35111661, 2021). "Finally, the top three genes (STEAP3, LTF, and HMOX1) with the greatest importance were chosen as key prognostic IMRGs for gliomas." (PMID 37545464, 2024). "STEAP3 expression was significantly positively associated with epithelial-to-mesenchymal transition (EMT) in GBM, but not all glioma types." (PMID 37009153, 2023). "A number of studies have found that upregulation of STEAP3 is strongly associated with poor prognosis in triple-negative breast cancer as well as gliomas, suggesting that STEAP3 may be used as a specific predictor." (PMID 38440354, 2024). "However, previous studies of CAPG, FANCD2, HMOX1, HSPB1, RRM2, and STEAP3 did not develop any new clinical therapy in glioma." (PMID 36566214, 2022). "CERES scores of 98.305% (58/59), 71.186% (42/59), and 45.763% (27/59) cells were negative in glioma cells after LTF, STEAP3, and HMOX1 knockout, respectively." (PMID 37545464, 2024).
hepatocellular carcinoma (9 papers, 2017 to 2025). A malignant tumor that arises from hepatocytes. "STEAP3, an iron reductase, was associated with the infiltration of immune cells in hepatocellular carcinoma and induced PD‐L2 expression." (PMID 37344930, 2023). "We observed the silencing of SERPING1 and STEAP3 in hepatocellular carcinoma tissues—genes that significantly impact clinical outcome." (PMID 39853609, 2025). "Due to its expression being remarkably diminished in HCC nodules compared with cirrhotic peritumoral tissues, STEAP3 was reported to be a marker of the transition from cirrhosis to hepatocellular carcinoma." (PMID 34741044, 2021). "In hepatocellular carcinoma (HCC), lower expression of the STEAP3 copper reductase and heavy Cu isotope enrichment have been reported for the tumor mass, relative to the surrounding tissue." (PMID 28303916, 2017).
prostate carcinoma (9 papers, 2014 to 2023). A carcinoma that arises from epithelial cells of the prostate gland. "Its role in metal Fe3+ and Cu2+ reduction for transmembrane transfer into cells can be carried on by STEAP3 metalloreductase associated with prostate cancer tumor suppression through induced apoptosis." (PMID 36304279, 2022). "Some researchers reported that STEAP3 are naturally processed CTL epitopes possessing anti‐prostate cancer reactivity in vivo and exhibited great potential for immunotherapy." (PMID 37344930, 2023). "The six-transmembrane epithelial antigen of prostate family member 3 (STEAP3) was first discovered in prostate tissues as a potential target for prostate cancer immunotherapy, also known as tumor suppressor activated pathway-6 (TSAP6)." (PMID 37386521, 2023). "STEAP3 was first found in prostate tissues and proposed as a candidate for prostate cancer immunotherapy." (PMID 34778263, 2021). "Further, STEAP3 may elicit specific cytotoxic lymphocyte responses and can be a promising candidate for prostate cancer immunotherapy." (PMID 37344930, 2023). "In prostate cancer, STEAP1, STEAP2, and STEAP4 are overexpressed, while STEAP3 expression is downregulated." (PMID 36011027, 2022). "Furthermore, ectopic expression of STEAP3 coupled with cisplatin exhibited additive effects on growth suppression and apoptosis in DU145 prostate carcinoma cells." (PMID 34790664, 2021).
glioblastoma (8 papers, 2021 to 2026). The most malignant astrocytic tumor (WHO grade IV). "Increased levels of STEAP3 expression are associated with a worse prognosis in a diverse variety of tumor types, including glioblastoma, breast carcinomas, and renal cell carcinoma." (PMID 37344930, 2023). "In our study, we downloaded information from public databases and found that STEAP3 expression was significantly higher in many tumors than in normal tissues, especially glioblastoma, pheochromocytoma, thymoma, and OC." (PMID 38440354, 2024). "STEAP3 can predict outcomes in clear cell renal cell carcinoma, pancreatic adenocarcinoma, uveal melanoma and glioblastoma." (PMID 35845961, 2022). "Using combined analysis of GEO and TCGA datasets, it was shown that STEAP3 is hypomethylated and consequently upregulated in glioblastoma, and may be used as a potential methylation-based prognostic biomarker." (PMID 34833128, 2021). "In addition, the authors suggested that STEAP3 is a potential target for glioblastoma treatment." (PMID 34833128, 2021).
bladder cancer (6 papers, 2021 to 2025). "The results showed that compared with corresponding normal tissues, STEAP3 was up-regulated in bladder cancer, blood cancer, brain cancer, cervix cancer, colon cancer, kidney cancer, lung cancer, ovary cancer, pancreas cancer and thyroid cancer tissues." (PMID 36424540, 2022). "The proliferation of cancer cells, including, pancreatic cancer, colorectal cancer and bladder cancer may be facilitated by the overexpression of STEAP3, which promotes iron uptake and storage." (PMID 37608887, 2023). "Most cancers, including head and neck squamous cell carcinoma (HNSC) and bladder cancer (BLCA), have increased STEAP3, whereas it was downregulated in some cancers, such as breast cancer (BRCA)." (PMID 39853609, 2025).
ovarian cancer (6 papers, 2022 to 2025). A primary or metastatic malignant neoplasm involving the ovary. "STEAP3 has been identified as being upregulated in ovarian cancer cells, and its potential as a prognostic marker for ovarian cancer patients has been validated." (PMID 38028615, 2023). "The expression of CYBRD1, LRP2, TFRC, SLC22A17, HEPH, SLC39A14, and PCBP2 involved in iron import was associated with poor OS of ovarian cancer, whereas the expression of LCN2, CP, SLC46A1, STEAP3, and LTF in this process was associated with improved OS in ovarian cancer." (PMID 38186569, 2023). "Conversely, 8 genes showed increased expression in ovarian cancer tissues, including LCN2, CP, TFR2, LRP2, MELTF, LTF, SLC11A2, and STEAP3." (PMID 38186569, 2023).